HIF1A (hypoxia inducible factor 1 subunit alpha)
Diseases named in the same sentence as HIF1A in open-access papers (continued):
Sharing a sentence is not in itself a finding about the gene and the disease.
myocardial ischemia (continued). "HIF-1α can upregulate mitophagy, mitochondrial autophagy, in cardiac cells through HIF-1α/(BNIP3) BCL2 and adenovirus E1B 19-kD-interacting protein 3 pathways, thereby stimulating their survival following myocardial ischemia-reperfusion." (PMID 35205167, 2022). "Berberine mediates BNIP3 expression by enhancing the binding of HIF-1α to the BNIP3 promoter, thereby inducing cardiomyocyte proliferation and autophagosome formation to inhibit cardiomyocyte apoptosis and myocardial ischemia/reperfusion injury." (PMID 36187470, 2022). "Regulated by HIF-1α, BNIP3 changes the mitochondrial permeability, and promotes mitochondrial autophagy ultimately during myocardial ischemia-reperfusion injury." (PMID 32140105, 2020). "Under the conditions of cardiac ischemia, the upregulation of HIF-1α can improve myocardial tolerance for acute I/R injury, which is attributed to the HIF-1α-mediated upregulation of the downstream component VEGF." (PMID 28659817, 2017). "In summary, this study systematically elucidates HL4’s cardioprotective mechanism via the STAT3/HIF-1α axis, providing a robust scientific foundation for its clinical application and laying groundwork for developing STAT3-targeted therapies for myocardial ischemia-reperfusion injury." (PMID 41268446, 2025). "Additional research exploring the effects of different oxygen partial pressures on the stabilization of HIF-1α and HIF-2α in cardiomyocytes would provide valuable insights into their specific roles and potential therapeutic implications for myocardial ischemia and reperfusion injury." (PMID 37233182, 2023). "To date, the HIF-1α/MIF axis has been investigated in multiple experimental models including cardiomyocyte and smooth muscle cell cultures after induction of hypoxia, in mouse models of myocardial ischemia/reperfusion injury, and in cancer." (PMID 29027966, 2017). "HIF-1α and HO-1 levels may predict cardiac ischemia and adverse cardiac events during non-cardiac surgery." (PMID 23526997, 2013).
preeclampsia (77 papers, 2008 to 2026). Preeclampsia is a hypertensive disorder of pregnancy that is characterized by new-onset hypertension with proteinuria presenting after 20 weeks of gestation, and depending on mild or severe forms may initially present with severe headache, visual disturbances, and hyperreflexia. "The aim of this study is to determine the pattern of HIF-1A expression in placenta, and to correlate its association with preeclampsia, fetal growth restriction and adverse perinatal outcomes." (PMID 40804807, 2025). "Increased placental HIF-1A after 12 weeks of gestation has been found to be associated with preeclampsia in humans." (PMID 40804807, 2025). "Serum TMAO and NT-proBNP were positively associated with disease severity in patients with gestational hypertension, but HIF-1α was negatively correlated with disease severity (P < 0.05)." (PMID 36987419, 2023). "High levels of HIF-1α in term placentas are associated with placental pathologies such as preeclampsia and intrauterine growth retardation." (PMID 36982514, 2023). "Placental hypoxia occurs in diseases such as gestational iron deficiency anemia, associated with increased accumulation of HIF-1α, similar to preeclampsia." (PMID 37206444, 2023). "All in all, serum TMAO, NT-proBNP and HIF-1α in patients with gestational hypertension are linked with disease severity, and have predictive and evaluative values for disease severity and pregnancy outcome." (PMID 36987419, 2023). "Serum TMAO, NT-proBNP and HIF-1a in patients with gestational hypertension are associated with disease severity and cardiac function, and have predictive and evaluative values for disease severity and pregnancy outcome." (PMID 36987419, 2023). "This study discovered that serum TMAO, NT-proBNP were positively associated with the disease severity in patients with gestational hypertension, but HIF-1α was negatively associated." (PMID 36987419, 2023). "Taken together, these observations suggest a role for the evolution-related UCA1 in the HIF1α-induced adaptive pathogenic mechanism of preeclampsia, promoting the survival of hypoxic trophoblasts and injuring maternal endothelial cells." (PMID 36160709, 2022). "Genetic and pharmacological manipulations causing increased HIF1A signaling in pregnant mice have indeed led to complications resembling preeclampsia." (PMID 36227697, 2022). "The both SNPs of HIF1A gene were significantly associated with preeclampsia, but another study found their insignificant association." (PMID 35972942, 2022). "Various murine models have interrogated the role of hypoxia in development of preeclampsia, including mice overexpressing HIF1A and mice deficient in catechol-O-methyltransferase that produce the HIF1A inhibitor 2-methoxyestradiol." (PMID 36227697, 2022). "In summary, while preeclampsia is a spontaneous and multifactorial disease, placental hypoxia and associated HIF1A expression are key features of severe preeclampsia." (PMID 36227697, 2022). "Persistent high expression of HIF1α in the placenta is one of the pathogenic mechanisms of preeclampsia." (PMID 36160709, 2022). "The downregulation of PHD-1, -2, and -3, which are regulators of the HIF-1α stability, is associated with preeclampsia." (PMID 35769460, 2022). "In humans, elevated levels of placental HIF-1α, beyond the first trimester, are strongly associated with preeclampsia." (PMID 34276401, 2021). "Hypoxia and elevated levels of hypoxia-inducible factor 1 alpha (HIF-1α) protein have also been noted in the placenta and are strongly associated with preeclampsia." (PMID 34276401, 2021). "Two placental single-nucleotide polymorphisms in the coding region of HIF1A have been associated with preeclampsia as well as elevated HIF-1α activity." (PMID 34831277, 2021). "Elevated levels of Hif-1α in the human placenta have been linked to the development of pregnancy-associated disorders, such as preeclampsia and fetal growth restriction." (PMID 30808910, 2019).
preeclampsia (continued). "Feto-placental hypoxia, hallmarked by increased levels of HIF1α, has been associated with development of preeclampsia." (PMID 29316938, 2018). "In the context of preeclampsia, molecular disturbances linked to the upregulation of microRNA-210 significantly contribute to the disruption of trophoblastic functions, angiogenesis, mitochondrial metabolism, and activation of the HIF-1α signalling pathway." (PMID 41226989, 2025). "However, no report clearly points out its association with serum TMAO and HIF-1α and cardiac function and pregnancy outcome in patients with gestational hypertension." (PMID 36987419, 2023). "The results of this study clarified that serum TMAO, NT-proBNP, and HIF-1α in patients with gestational hypertension were linked with LVEDV, LVESV, and LVEF values, suggesting that serum TMAO, NT-proBNP, and HIF-1α were implicated in cardiac function in patients." (PMID 36987419, 2023). "However, excess of HIF1A in other organs than placenta and associated fetal/maternal morbidities are confounding these murine models of preeclampsia." (PMID 36227697, 2022). "While HIF-1α overactivation as a cause of preeclampsia may seem contradictory to the notion that HIFs are essential for angiogenesis, there is likely an optimal amount of activation, which may be dysregulated in preeclamptic pregnancies." (PMID 34831277, 2021). "Accumulation of HIF-1α is commonly an acute and beneficial response to hypoxia; when chronically elevated, this protein is associated with multiple disease conditions, including preeclampsia." (PMID 33652665, 2021). "Previous studies showed that women with preeclampsia had persistent elevated placental HIF-1α levels that enhanced the transcription of genes that encoded soluble fms-like tyrosine kinase-1 (sFlt-1), soluble endoglin (sEng), and endothelin-1 (ET-1), all known to contribute to preeclampsia." (PMID 33758274, 2021). "In addition, elevated levels of placental HIF-1α, beyond the first trimester, have been associated with preeclampsia in humans." (PMID 30808910, 2019). "We previously reported that autophagy in EVTs was inhibited by soluble endoglin in preeclamptic placentas as one of the causes for the pathophysiology of preeclampsia, and the overexpression of HIF1α was significantly higher in placental biopsies from preeclampsia than in normal placentas." (PMID 24098539, 2013). "In this work, we studied whether either or both HIF1A variants contribute to preeclampsia susceptibility." (PMID 21414224, 2011). "Thus, HIF1α is considered a pathogenic molecule involved in preeclampsia." (PMID 36160709, 2022). "Therefore, insufficient Hif1α expression in either the maternal or fetal side of the placenta may be associated with impaired vascular development similar to that seen in preeclampsia." (PMID 32784053, 2020). "Interestingly, hypoxia suppresses primary cilium formation, and elevated levels of HIF-1α in the human trophoblasts have been linked to the development of preeclampsia, suggesting placental hypoxia-activated HIF-1α plays a key role in the pathogenesis of preeclampsia." (PMID 32389123, 2020). "Protective effects on ovarian reserve in primary ovarian insufficiency, anti-inflammatory and anti-ferroptotic actions in endometritis, and suppression of sFlt-1 and HIF-1α in preeclampsia further highlight its relevance to reproductive pathology." (PMID 41821610, 2026). "Disruption of this crucial axis results in persistent HIF1A levels, leading to placental pathologies such as preeclampsia." (PMID 41167398, 2025). "In the present study, we capitalized on our murine Phd2−/− cKO model of early-onset preeclampsia, characterized by placental hypoxia and sustained HIF1A levels." (PMID 41167398, 2025). "In preeclampsia, there is reduced oxygenation in the placenta due to abnormal trophoblast invasion and poor spiral artery remodelling, leading to increasing HIF-1A in the placenta." (PMID 40804807, 2025).
preeclampsia (continued). "Curiously, the HIF1α target genes more related to preeclampsia, such as interleukin 1 β and vascular endothelial growth factor alpha, trended to be augmented, but not significantly, in both FC and FF dams compared to the control group." (PMID 38276547, 2024). "Similar to HIF-1α, Mfn-2 also shows an increase secondary to placental hypoxia, playing a role in the pathophysiology of preeclampsia as a key transcription factor regulating cellular responses to hypoxia and low oxygen tension." (PMID 39166673, 2024). "Circulating and uteroplacental levels of miR-210, a target of HIF-1α, are increased in preeclampsia, in high-altitude pregnancy, and in a high-altitude hypoxic sheep model of preeclampsia." (PMID 36674858, 2023). "Serum TMAO and NT-proBNP in patients with gestational hypertension were positively correlated but HIF-1a was negatively correlated with the severity of the disease (P < 0.05)." (PMID 36987419, 2023). "As a result of preeclampsia, an increase was observed in HIF-1α and ET-1 protein levels in the placenta." (PMID 37194760, 2023). "Serum TMAO, NT-proBNP and HIF1a were associated with LVEDV, LVESV and LVEF values in patients with gestational hypertension (P < 0.05)." (PMID 36987419, 2023). "The serum TMAO, NT-proBNP, and HIF-1α were associated with LVEDV, LVESV, and LVEF values in patients with gestational hypertension (P < 0.05)." (PMID 36987419, 2023). "Analysis of the relation of serum TMAO, NT-proBNP and HIF-1a with the severity of disease and cardiac function indexes in patients with gestational hypertension was conducted." (PMID 36987419, 2023). "Females with preeclampsia showed elevated HIF1A mRNA expression in placenta, which was 3-fold higher than that of control women." (PMID 36249421, 2022). "Based on these findings, we developed a novel theory of preeclampsia, namely, a HIF1α-induced adaptive mechanism." (PMID 36160709, 2022). "Trophoblastic overexpression of constitutively active HIF1A in mice reproduces preeclampsia-like symptoms, although fetal weight was only reduced at birth, contrasting early growth restriction in human E-PE." (PMID 36227697, 2022). "Similar preeclampsia-like features were observed in mice overexpressing constitutively active HIF1A in trophoblasts, except for early-onset fetal growth restriction." (PMID 36227697, 2022). "Preeclampsia is a species-specific disease related to placental evolution and the HIF1α-induced hypoxia adaptation." (PMID 36160709, 2022). "UCA1 is a human-specific lncRNA regulated by HIF1α and is involved in the pathogenesis of preeclampsia." (PMID 36160709, 2022). "We reported that urothelial cancer associated 1 (UCA1) is a potential mediator because it is a human-specific long noncoding RNA (lncRNA) that is upregulated in placental tissues and maternal serum from women with preeclampsia and is regulated by HIF1α." (PMID 36160709, 2022). "Then, UCA1 was confirmed to be a hypoxia-responsive and HIF1α-regulated lncRNA, similar to other studies in cancers, suggesting that UCA1 is a downstream molecule of the HIF1α pathway and hypoxia responses in women with preeclampsia." (PMID 36160709, 2022). "We reasoned that a placenta-specific Phd2 deletion in mice would better recapitulate the early-onset spectrum of preeclampsia than broad trophoblastic overexpression of constitutively active HIF1A." (PMID 36227697, 2022). "Persistently increased HIF1α expression was observed in preeclamptic placentae; overexpression of HIF1α in pregnant animals resulted in several symptoms of preeclampsia." (PMID 36160709, 2022). "The results of this study revealed that the serum HIF-1α level had a good predictive value when used alone or in combination with uterine artery Doppler to predict preeclampsia during the first trimester screening process." (PMID 33758274, 2021). "There are some data indicating that women with preeclampsia are characterized by persistently elevated placental HIF-1α levels." (PMID 33652665, 2021).
preeclampsia (continued). "For pregnancies complicated by preeclampsia, HIF-1α expression remains abnormally elevated and the trophoblasts development remains arrested at an immature stage, causing a shallow trophoblast invasion." (PMID 33758274, 2021). "Previous studies found that pregnant women with preeclampsia had high blood levels of HIF-1α compared to normal healthy controls." (PMID 33758274, 2021). "Additional studies with a larger sample size of early-onset preeclampsia and other models using serum HIF-1α levels combined with uterine artery Doppler, maternal characteristic risk factors, or other biomarkers should be conducted." (PMID 33758274, 2021). "Pregnant mice with global overexpression of HIF-1α display phenotypes of preeclampsia and FGR, showing elevated blood pressure, proteinuria and reduced fetal weight." (PMID 33800426, 2021). "On the other hand, elevated levels of miR-106a prevented oxidative stress injury and inflammation in hepatic mouse with gestational hypertension, resulting to repression of the expressions of HIF1-α and VEGF in diabetic retina." (PMID 35237654, 2021). "Further studies should be conducted to evaluate first trimester angiogenic factors and HIF-1α in preeclampsia." (PMID 33758274, 2021). "The objective of this study was to determine the predictive value of serum hypoxia-inducible factor-1α (HIF-1α) combined with uterine artery Doppler in singleton pregnancy during 11–13+6 weeks of gestation for preeclampsia." (PMID 33758274, 2021). "Serum HIF-1α levels were higher than 1.45 multiple of median for the gestational age as a cut-off value for predicting preeclampsia; the sensitivity, specificity, PPV, and NPV were 66.7%, 71.5%, 17.2%, and 96.2%, respectively." (PMID 33758274, 2021). "A number of growth factors/cytokines with angiogenic properties have been actively studied in the context of preeclampsia, including HIF-1α, PIGF, TGF-β, and VEGF." (PMID 33652665, 2021). "Pregnancy at high altitude is associated with ~3-fold increases in the incidence of preeclampsia and FGR and overexpression of placental HIF-1α." (PMID 33800426, 2021). "The strength of this study was that this is the first prospective study that used serum HIF-1α levels combined with uterine artery Doppler in the first trimester to predict preeclampsia." (PMID 33758274, 2021). "Thus, we speculate that a down-regulation of Hif1α is caused by a deficiency in Hmox1, which could also occur in these trophoblast cells, and are well known for their role in SA remodeling, the failure of which is likely a contributing cause of preeclampsia." (PMID 32784053, 2020). "In early-onset preeclampsia, both HIF1A and FIH1 deSUMOylation by SENP3 was significantly elevated in the human placenta, and this partly contributes to increased HIF1A activity and stability in physiological and pathological conditions." (PMID 33192553, 2020). "It has been revealed that placental hypoxia and oxidative stress induce the genesis of preeclampsia, and the high expression level of HIF1A in preeclampsia is partially due to alteration of HIF1A hydroxylation." (PMID 33192553, 2020). "As for HIF1α as the treatment target of preeclampsia, hyper-expression of HIF1α by hypoxia/reoxygenation was shown to be reduced by melatonin, which protected the syncytiotrophoblasts by restoring autophagy." (PMID 32392703, 2020). "Clinical studies showed upregulation of HIF-1α in trophoblasts of patients with missed abortions, and increased HIF-1α activity in placental tissues has been associated with preeclampsia." (PMID 30804946, 2019). "Decreased expression of HIF1α has previously been reported in placental tissue from pregnancies complicated by preeclampsia compared to normal pregnancies." (PMID 29316938, 2018). "A placental mRNA/miRNA network involving microRNA (miR)-210, iron sulfur-cluster assembly enzyme (ISCU) and HIF1α was proposed to regulate mitochondrial function during preeclampsia." (PMID 29316938, 2018).